IL6 (interleukin 6)
Diseases named in the same sentence as IL6 in open-access papers (continued):
Sharing a sentence is not in itself a finding about the gene and the disease.
schizophrenia (continued). "In the present study, we report significant association of SNPs in pro-inflammatory cytokine genes IL1A, IL6, TNFA, and IFNG with schizophrenia in the Malayalam-speaking Dravidian population of India." (PMID 27177030, 2016). "The higher levels of IL-6 and TNF-α (7.98±.67 and 40.76±6.98 pg/ml) were recorded in the newly diagnosed schizophrenia patients." (PMID 28083028, 2016). "These abnormalities of the humoral factors, including IL-6 and soluble MMP3 after polyI:C treatment, impair neuronal development, resulting in psychiatric disorders such as schizophrenia and ASD." (PMID 26633355, 2015). "Previous studies have revealed a positive relationship between plasma IL-6 and the severity of positive symptoms in subjects with ARMS and veterans with schizophrenia." (PMID 25214388, 2015). "Shreds of evidence from preclinical and clinical studies have shown persistent elevation in various inflammatory markers like TNF-α, IL-12, IL-1β, IL-6, IL-1, and interferon (IFN)-γ in first onset and acute relapse schizophrenia subjects who were on antipsychotic medications." (PMID 39907868, 2025). "Among them, the higher OR values of IL-6 and CRP suggested that they might be the core driving factors for the occurrence of MS in patients with schizophrenia." (PMID 41450839, 2025). "Furthermore, heightened neurotoxicity resulting from elevated concentrations of toxic cytokines (e.g., IL-1β, IL-6, IL-8, TNF-αand IFN-γ) and chemokines (e.g., CCL11, CCL2, CXCL8 and CXCL10) is markedly correlated with the schizophrenia phenome." (PMID 41200225, 2025). "Similar to IL-6, TNF-α is associated with more severe negative symptoms in schizophrenia and other psychotic disorders." (PMID 39858450, 2025). "We found that higher plasma IL-6 levels were significantly related to more severe depressive symptoms in early schizophrenia and more severe negative symptoms in established schizophrenia." (PMID 39911538, 2025). "IL-6 levels have also been positively correlated with the negative and cognitive symptoms of schizophrenia, potentially via its effects on NMDA receptors and GABAergic interneurons." (PMID 40358174, 2025). "Higher plasma IL-6 levels were related to more severe depressive symptoms in early schizophrenia (p < .05) and negative symptoms in established schizophrenia (p < .05)." (PMID 39911538, 2025). "Viral recognition by microglial Toll-like receptors (TLR2, TLR3, TLR9) triggers robust neuroinflammatory responses characterised by elevated key pro-inflammatory mediators such as IL-6, TNF-α, and IL-1β, patterns consistently observed in patients with schizophrenia." (PMID 40806558, 2025). "We evaluated whether higher plasma IL-6 levels would be associated with more severe negative or depressive symptoms in schizophrenia and explored how these associations might differ across stages of illness by utilizing early and established schizophrenia cohorts." (PMID 39911538, 2025). "Elevated IL-6 and higher neutrophil count from bone marrow hyperactivity are not uncommon in patients with schizophrenia and can be explained as a reflection of immune dysregulation." (PMID 39816323, 2024). "The finding that pro-inflammatory cytokines IL-6, TNF-α and IFN-γ had the greatest influence in the network is consistent with previous research that has demonstrated elevated mean levels of pro-inflammatory cytokines in individuals with schizophrenia." (PMID 37723153, 2023). "This adds further to the suggestion that targeting IL-6 may weaken a pro-inflammatory state and influential pro-inflammatory cytokines IL-6, TNF-α and IFN-γ might represent important biomarkers, and key targets for immune-based therapies in schizophrenia." (PMID 37723153, 2023). "Significantly higher IL-6 levels in patients with deficit schizophrenia were observed in females, but not in males." (PMID 37370004, 2023).
schizophrenia (continued). "According to the studies, antipsychotics affect IL-6 levels; however, it does not return to normal levels, indicating the active macrophage system in schizophrenia." (PMID 37644489, 2023). "In an analysis of a larger CSF dataset, both IL-6 and IL-8 were found to be significantly elevated in schizophrenia patients as compared to controls, an effect not found in affective disorder patients." (PMID 37850104, 2023). "In this study, IL-6 levels were elevated but not above baseline levels in patients with acute schizophrenia, and the difference was not statistically significant after excluding confounding factors." (PMID 38066312, 2023). "Here, we analyzed changes in serum concentrations of cytokines (IL-1β, IL-2, IL-4, IL-6, IL-10, IL-21, APRIL, BAFF, PBEF/Visfatin, IFN-α, and TNF-α) and growth/neurotrophic factors (GM-CSF, NRG1-β1, NGF-β, and GDNF) in patients with schizophrenia in an exacerbation phase." (PMID 37239308, 2023). "Meta-analytical schizophrenia data have found that the blood and CSF levels of IL-1β, IL-6, and IL-8, but not IL-2, were increased." (PMID 37510730, 2023). "Some signs of inflammation, such as IL-6 and TNF-α, overlap in both MDD and schizophrenia." (PMID 37280213, 2023). "Immune stalling of virus-infected DC and/or PVM cells might explain the concurrent release of pro- (IL-6 and IL-8) and anti-inflammatory (IL-10 and TGF-ß) cytokines in schizophrenia." (PMID 37850104, 2023). "Activation of the Il-6/NOX2 pathway in a mouse model of schizophrenia elevates oxidate stress, perturbs the normal development and maturation of PV+ cortical interneurons, and contributes to the emergence of schizophrenia like behavioral deficits." (PMID 36311505, 2022). "Serum IL-6 levels are significantly higher in patients with schizophrenia, and there is a negative correlation between IL-6 and cognition." (PMID 35887634, 2022). "Furthermore, increased levels of IL-1β, IL-6, IL-17, IL-21, IL-22, IL-23, and tumor necrosis factor (TNF)-α were all found to be inversely related to HR-QoL in these schizophrenia patients." (PMID 36011997, 2022). "On the other hand, when IL-6 is eliminated by co-administration of cytokine neutralizing antibodies targeted against IL-6, or by genetic manipulation, schizophrenia-like abnormalities are not detectable in the offspring." (PMID 35963926, 2022). "The first major finding of this study is that IL-23, IL-6, IL-17, and TNF-α were considerably greater in MNP than in SNP, while IL-1β, IL-22, G-CSF, IL-21, IL-17, IL-10, and TNF-α were significantly higher in schizophrenia than in controls." (PMID 36256663, 2022). "HPA-axis dysregulation associated with hypercortisolemia has been reported in psychotic patients and might be elicited by pro-inflammatory cytokines such as IL-1, IL-6, and TNF-α in schizophrenia." (PMID 35963926, 2022). "In acute psychosis, schizophrenia, SARS-CoV-1, and SARS-CoV-2, however, there is disruption of the glucocorticoid-immune circuits such that both IL-6 and cortisol may be elevated." (PMID 34648616, 2022). "Moreover, we showed that a reliable latent vector could be extracted from the IL-6/IL-23/Th17, G-CoDe and phenome scores, thereby shaping a new pathway phenotype reflecting the link among peripheral adverse outcome pathways and the cognitome and phenome of schizophrenia." (PMID 36256663, 2022). "The fewest relations were observed between cytokine levels and negative symptoms of schizophrenia: only IL-1, IL-6, IL-13, and TNF-β were positively correlated with the negative-symptom PANSS score." (PMID 36556337, 2022). "Most importantly, during inflammatory responses, IL-22 is upregulated in the brain and may increase the production of TNF-α, IL-6, and prostaglandins and induce STAT3, MAP-kinase, and JAK-STAT pathways, which all play a role in schizophrenia." (PMID 36256663, 2022). "Thus, an increase in the expression of IL-6 leads to the overstimulation of both HMGB1 and DKK1 in schizophrenia." (PMID 35269952, 2022).
schizophrenia (continued). "CCL2, coming from either myeloid cells or astrocytes, can influence the differentiation of tissue macrophages and promotes the production of proinflammatory cytokines including IL-6, IL-1β, and TNF-α which are all elevated in the brains of people with high inflammation schizophrenia." (PMID 35844224, 2022). "Increased IL-22 and IL-6, but not IL-17 or IL-1β, were observed in schizophrenia as compared with healthy subjects." (PMID 36256663, 2022). "The mechanisms by which clozapine causes inflammation are not fully understood; nevertheless, it has been reported that pro-inflammatory cytokines, such as interleukin-6 (IL-6) and tumor necrosis factor-α (TNF-α), are elevated in patients with schizophrenia treated with clozapine." (PMID 36271340, 2022). "For example, a meta-analysis of 68 studies found discretely elevated levels of the proinflammatory cytokines IL-6 and TNF-α in acutely ill patients with schizophrenia, bipolar disorder, and major depressive disorder (MDD) compared with non-psychiatrically ill control subjects." (PMID 34650454, 2021). "Likewise, IL-12, IL-6, TNF and IFNγ peripherical levels are enhanced in patients with schizophrenia, and IL-6 and IL-10 levels elevated in children with ADHD." (PMID 34610039, 2021). "Concerning schizophrenia, a meta-analysis reported increased levels of IFN-γ, IL-1RA, IL-1β, IL-6, IL-8, IL-12, sIL-2R, TGF-β and TNF-α in acutely ill patients (i.e. acutely psychotic) with chronic schizophrenia and a significant decrease in IL-1β, IL-4 and IL-6 following treatment." (PMID 34584171, 2021). "On the other hand, few other studies have not found differences between serum CRP or IL-6 levels of patients with schizophrenia and control subjects." (PMID 34465310, 2021). "Beyond IL-6, TNF-α is associated with schizophrenia-negative outcome, and thus can be considered a novel drug target for schizophrenia therapy." (PMID 33746786, 2021). "Also we investigated associations between some immunological patterns and markers of inflammatory response (CRP, IL-2, IL-6, IL-10, the activity of LE and a1-PI, antibodies to S100B and MBP) with clinical symptoms in schizophrenia." (PMID 34025476, 2021). "Such elevated levels of IL-8, IL-6, and TNF-α imply that schizophrenia might represent an autoimmune neuropsychiatric spectrum disorder that may emerge during an autoimmune CNS disease." (PMID 33746786, 2021). "Therefore, we investigated inflammation in the SEZ by defining those with low and high levels of inflammation using cluster analysis of IL6, IL6R, IL1R1 and SERPINA3 gene expression in 32 controls, 32 schizophrenia and 29 bipolar disorder cases." (PMID 34911938, 2021). "A number of studies among patients with first episode and persistent or recurrent schizophrenia have shown increased serum levels of acute phase proteins, such as CRP, and proinflammatory markers such as tumor necrosis factor (TNF-alpha), IL-6, and IL-1β, although with some inconsistency." (PMID 34465310, 2021). "TNF-α and IL-6 were associated with the deficit syndrome, and TNF-α predicted blunted affect, alogia, and total negative symptoms in schizophrenia patients." (PMID 34199832, 2021). "Finally, in patients with schizophrenia, the Th1/Th2 ratio (defined as [IFN-γ]/[IL-4]) showed a significant positive correlation with admission levels of plasma IL-6 and plasma TNF-α." (PMID 32061259, 2020). "For example, we do not find a difference in IL-6 concentration, which has consistently been shown to be increased in patients with schizophrenia relative to controls." (PMID 32238816, 2020). "IL-6 and TNF-α levels are elevated in schizophrenia and animal models." (PMID 32296347, 2020). "There was also trend level evidence for an association between PRS-schizophrenia and CRP (β = 0.05; 95% CI, −0.01–0.10, p = .061) but not with IL-6 (β = 0.01; 95% CI, −0.04-0.09, p = .670)." (PMID 32828613, 2020).
schizophrenia (continued). "We measured in 46 patients with schizophrenia and MetS serum levels of adiponectin insulin, leptin, TNF-α and IL-6 and compared these levels to those of patients with schizophrenia without MetS." (PMID 33066473, 2020). "Cross-sectional studies have linked inflammatory parameters in the blood, including C-reactive protein as well as interleukin-6 and interleukin-8, to severity of negative symptoms and cognitive performance in schizophrenia patients." (PMID 31354535, 2019). "In this study, serum OXT, OXT receptor (OXTR), interleukin-6 (IL-6), high sensitivity CRP (hsCRP) and homocysteine (Hcy) levels were measured in 52 first-episode schizophrenia (FES) patients and 41 healthy controls (HC) from the Second Xiangya Hospital of Central South University." (PMID 31024366, 2019). "Studies have repeatedly (although not invariably) shown that patients with schizophrenia have increased serum concentrations of pro-inflammatory cytokines, including IL-1β, IL-6 and TNF-α." (PMID 30355368, 2019). "In contrast, IL-6 was not different between groups in a sample of 125 bipolar, 186 schizophrenia, and 244 control participants." (PMID 29803226, 2018). "While longitudinal studies are needed to truly evaluate this hypothesis, the theory is consistent with findings that IL-1β as well as IL-6 and TGF-β may reflect state markers for schizophrenia." (PMID 29803226, 2018). "Besides its potential function as a biomarker for schizophrenia, CRP is also synthesized by hepatocytes under the regulatory control of IL-6, released by macrophages and adipocytes." (PMID 29434554, 2018). "On the contrary, our findings did not confirm elevation of IL-6 in first-episode psychosis and schizophrenia in relapse." (PMID 29163240, 2017). "Others presented results of positive correlation between IL-6 serum levels and negative symptoms severity in drug-naive male patients with schizophrenia." (PMID 29163240, 2017). "It has been observed in preclinical studies that maternal immune activation in rodents induces inflammatory cytokines (IL-1β, IL-6, TNF) and reduces anti-inflammatory cytokines (IL-10) in both the maternal fluids and in the fetal brain, inducing schizophrenia-like behaviors in the offspring." (PMID 28620379, 2017). "We found that peripheral PBMC IL-6 mRNA levels, in the absence of any other information, reliably discriminated between a diagnosis of schizophrenia and normal controls." (PMID 27206977, 2016). "Furthermore, in the schizophrenia group, SERPINA3 (ρ=0.397, P=0.016) and IL-6 (ρ=0.464, P=0.004) mRNAs were significantly positively correlated with antipsychotic (lifetime) intake." (PMID 27959331, 2016). "Pro-inflammatory cytokines such as tumor necrosis factor-α (TNF-α), IL-6, IL-1β, and interferon-γ (IFN-γ), formed by persistently actuated macrophages and T lymphocytes have also been conveyed as immunological altered components in schizophrenia." (PMID 27047333, 2016). "Previous work has explored the use of IL-6 as a clinical predictor, but for infection in febrile neutropenia, not schizophrenia." (PMID 27206977, 2016). "For individuals with schizophrenia, each inflammatory mRNA in OFC tissue was significantly correlated with its expression in the DLPFC tissue (SERPINA3 r=0.723, P<0.001; IL-1β r=0.744, P<0.001; IL-6 r=0.686, P<0.001; IL-8 r=0.417, P=0.022)." (PMID 27959331, 2016). "Additionally, a missense mutation in NRG1 has been reported to increase activation of proinflammatory cytokines such as interleukin 6 (IL-6), tumor necrosis factor α (TNF-α), and interleukin 8 (IL-8) in patients with schizophrenia." (PMID 27725886, 2016). "Our results indicate that elevated IL-6 in schizophrenia patients does not occur due to genetic variation in its gene." (PMID 25214388, 2015). "There is also one study showing a positive correlation between serum IL-6 and the severity of negative symptoms in drug-naïve schizophrenia males." (PMID 25214388, 2015).
schizophrenia (continued). "First, patients with schizophrenia (especially those previously untreated or not receiving medication for prolonged periods of time) have high plasma levels of IL-6 compared to healthy controls, and the increased levels correlate with acute phase." (PMID 25785244, 2015). "However, several studies investigating the role of proinflammatory cytokines like tumor necrosis factor (TNF) alpha or interleukins (IL1 beta, IL6, and IL8) have involved microglial activation in schizophrenia pathogenesis." (PMID 24381719, 2013). "Our results do not support the association of polymorphisms in IL2, IL6 and IFNG genes with schizophrenia." (PMID 24065520, 2013). "Furthermore, the resulting pro-inflammatory cytokine discharge, including interleukin-1β (IL-1β), IL-6, and TNF-α, and the disruption of the blood–brain barrier can collectively lead to the neurodevelopmental abnormalities characteristic of schizophrenia." (PMID 40806558, 2025). "Elevations of IL-1β, IL-6, IL-8, IL-4, and TNF-α may also exacerbate negative symptoms of schizophrenia, whereas IL-6, together with IL-13 and IL-17, may intensify general symptoms in chronic schizophrenia." (PMID 40364201, 2025). "In particular, deficit schizophrenia, a subtype marked by primary and persistent negative symptoms, has been more strongly correlated with increased levels of pro-inflammatory mediators including IL-6 and TNF- α compared to non-deficit forms." (PMID 40806558, 2025). "In individuals with established schizophrenia, some evidence suggests that negative symptoms rather than depressive symptoms may be related to higher peripheral IL-6 levels." (PMID 39911538, 2025). "We predicted that elevated plasma IL-6 levels would be related to greater depressive and negative symptom severity, particularly in individuals with early-stage schizophrenia, when the influence of antipsychotic medication and other illness-related confounders is less pronounced." (PMID 39911538, 2025). "Understanding the relationship between plasma IL-6 levels and depressive and negative symptoms may help unravel the heterogeneity of schizophrenia, paving the way for biologically informed substratification of patients in future experimental clinical research." (PMID 39911538, 2025). "Studies have shown that patients with schizophrenia exhibitelevated levels of monocytes, neutrophils, and C-reactive protein (CRP).Additionally, various cytokines (e.g., monocyte chemoattractant protein-1,IL-1β, IL-5, IL-6, IL-9 and TNF-α) have been reported to beupregulated in schizophrenia." (PMID 40926813, 2025). "In a 2015 study on 30 patients with schizophrenia, IL-6 and TNF-α levels were significantly elevated in the patient group treated with antipsychotics; this study also showed an immunological response in schizophrenia, despite the lack of factors that cause inflammation." (PMID 37644489, 2023). "Bulk RNAseq identified 156 up-regulated genes (FDR < 0.05) in MGL following acute IL-6 exposure, including IRF8, REL, HSPA1A/B and OXTR, which significantly overlapped with an up-regulated gene set from human post-mortem brain tissue from individuals with schizophrenia." (PMID 36781081, 2023). "Furthermore, although some previous studies have found that TRS patients had significantly higher IL-6 levels than patients with treatment-responsive schizophrenia, possible sex differences have not been expressly discussed yet." (PMID 37370004, 2023). "Another explanation may be that IL-6 is not specific to schizophrenia; some studies have shown that IL-6 is altered in both bipolar disorder and depressed patients, and that IL-6 is correlated with negative and positive symptoms." (PMID 36590607, 2022). "We, too, found no relation between IL-6 levels and schizophrenia duration." (PMID 36556337, 2022).